POMT1 (protein O-mannosyltransferase 1)
Description:
Transfers mannosyl residues to the hydroxyl group of serine or threonine residues. Coexpression of both POMT1 and POMT2 is necessary for enzyme activity, expression of either POMT1 or POMT2 alone is insufficient. Essentially dedicated to O-mannosylation of alpha-DAG1 and few other proteins but not of cadherins and protocaherins.
Synonyms: LGMD2K; LGMDR11; MDDGA1; MDDGB1; MDDGC1; RT
Tractability: Antibody: UniProt predicts a signal peptide or a membrane-spanning region. PROTAC: ubiquitination databases record sites on it; its protein half-life has been measured.
Gene: Protein-coding gene on chromosome 9 (131,502,789 to 131,523,806, forward strand). Ensembl gene ENSG00000130714.
Subcellular location: Endoplasmic reticulum membrane
Subcellular location (Human Protein Atlas): Golgi apparatus
Pathways (Reactome):
Metabolism of proteins: DAG1 core M1 glycosylations; DAG1 core M2 glycosylations; DAG1 core M3 glycosylations
Disease: Defective POMT1 causes MDDGA1, MDDGB1 and MDDGC1; Defective POMT2 causes MDDGA2, MDDGB2 and MDDGC2
Cell-Cell communication: Regulation of CDH1 posttranslational processing and trafficking to plasma membrane
Gene Ontology:
Molecular function: mannosyltransferase activity; dolichyl-phosphate-mannose-protein mannosyltransferase activity
Biological process: protein O-linked glycosylation via mannose; protein O-linked glycosylation
Cellular component: dolichyl-phosphate-mannose-protein mannosyltransferase complex; endoplasmic reticulum membrane; endoplasmic reticulum; membrane; acrosomal vesicle; sarcoplasmic reticulum
Genetic constraint (gnomAD): Loss-of-function variants: 90 observed, 107.07 expected, observed/expected ratio (o/e) 0.84, 90% interval 0.71 to 1. The upper end of that interval is the gene's LOEUF score, 1, which puts it in group 4 of 6, group 1 being the genes least tolerant of losing a copy. Missense variants: 857 observed, 953.05 expected, observed/expected ratio (o/e) 0.9, 90% interval 0.85 to 0.95. Synonymous variants: 371 observed, 393.64 expected, observed/expected ratio (o/e) 0.94, 90% interval 0.87 to 1.03.
Gene-disease validity (ClinGen):
ClinGen rates the evidence that POMT1 causes each of these diseases.
myopathy caused by variation in POMT1 (autosomal recessive): Definitive. Any myopathy in which the cause of the disease is a variation in the POMT1 gene.
Homologues: Orthologues: chimpanzee POMT1 (99% identical), macaque POMT1 (97% identical), dog POMT1 (89% identical), pig POMT1 (87% identical), mouse Pomt1 (86% identical), rat Pomt1 (84% identical), guinea pig POMT1 (80% identical), tropical clawed frog pomt1 (70% identical), zebrafish pomt1 (66% identical), Drosophila melanogaster rt (43% identical). Paralogues in human: POMT2 (33% identical), SDF2L1 (9% identical), SDF2 (9% identical).